CXCR4 (C-X-C motif chemokine receptor 4)
Diseases named in the same sentence as CXCR4 in open-access papers (continued):
Sharing a sentence is not in itself a finding about the gene and the disease.
ischemia (continued). "The increase of CXCR4 might indicate an accumulation of inflammatory reactions in human blood as an early warning for ischemia." (PMID 37305740, 2023). "However, CXCR4 expression significantly augmented compared with the basal level, coming in line with the significant increase in its expression in rats with ischemia relative to that in the control group observed in the current study." (PMID 34630958, 2021). "Additionally, post-treatment of rats with BM-MSCs significantly raised the gene expression level of CXCR4 compared with control and ischemia groups in the current work." (PMID 34630958, 2021). "We showed, for the first time, that systemic administration of Exo derived from CXCR4-overexpressing CPC improves heart function in a rat model of ischemia reperfusion injury These data represent a substantial step toward clinical application of Exo-based therapeutics in cardiovascular disease." (PMID 30678240, 2019). "The present study found that DHI could significantly up-regulate the expression of CXCR4 in ischemia gastrocnemius muscle and cultured EPCs." (PMID 31607924, 2019). "Recently, it has been found that both chemokine C-X-C motif ligand 12 (CXCL12) and its receptor CXCR4 were upregulated in spinal glial cells of mice with partial sciatic nerve ligation (pSNL)-induced neuropathic pain or chronic post-ischemia-induced inflammatory pain." (PMID 29386025, 2018). "Above all, we found that both atorvastatin and rosuvastatin could improve the recovery rate of capillaries after ischemia and up-regulate CXCR4 expression in ischemic tissues." (PMID 26309120, 2015). "In addition to its role in vascularization during development, the CXCL12/CXCR4 also plays an important role in angiogenesis in the context of ischemia, as discussed in more detail recently." (PMID 26347749, 2015). "Taken together, these data suggested that increased number of APJ+ stem cell at ischemia area via upregulation of SDF-1α/CXCR-4 pathway maybe responsible for apelin-BMCs therapy-mediated cardiac repair." (PMID 24039710, 2013). "In conclusion, this study demonstrates that ischemia mobilizes BM stem cells via miR-150/CXCR4 dependent mechanism and miR-150 may be a novel therapeutic target for stem cell migration to the ischemic tissue for neovascularization and repair." (PMID 22039399, 2011). "Our results reveled that hindlimb ischemia surgery may have induced more intense CXCR4 expression on circulating CD34+/Flk-1+ EPCs; treatment with either atorvastatin or rosuvastatin may have significantly up-regulated the relative intensity of CXCR4 expression on CD34+/Flk-1+ EPCs." (PMID 26309120, 2015). "Rats treated with BM-MSCs showed significantly raised gene expression levels of SDF-1, CXCR4, VEGFR2, and vWF compared with control and ischemia groups." (PMID 34630958, 2021). "Another protein upregulated by HIF-1α is CXCR4, a chemokine receptor for SDF-1α also known as CXCL12, whose expression occurs in hypoxic tumoral microenvironment conditions and vascular ischemia." (PMID 32599834, 2020). "Transgenic CXCR4-EGFP reporter mice were utilized to analyze CD45+/CXCR4-EGFP+ and CD45−/CXCR4-EGFP+ cell populations from BM and heart under normoxia and ischemia." (PMID 28550361, 2017). "In conclusion, the present study revealed that AMI induces MMP-2 release, which hampered the ischemia-induced increase in SDF-1α and CXCR4 by cleaving the SDF-1α/CXCR4 axis." (PMID 28299177, 2016). "In the present study, we found that brain SDF-1α expression is reduced at basal and that ischemia-induced up-regulation of brain SDF-1α and CXCR4 are less in db/db mice." (PMID 23185548, 2012). "In this study, we show that ischemia inhibits the expression of miR-150 in BM-derived mononuclear cells (MNC) and activates its target Cxcr4 gene." (PMID 22039399, 2011). "Moreover, downregulation of CXCL12/CXCR4 inhibits glial TLR4 activation in the spinal cord and alleviates pain in the ischemia-reperfusion-induced inflammatory pain model." (PMID 30647535, 2018).
ischemia (continued). "They did not examine the additive or synergistic effects of cilostazol on transplanted human EPCs in murine hindlimb ischemia, Matrigel angiogenesis models, nor the role of the SDF-1/CXCR4 system on the underlying mechanism." (PMID 27595100, 2016). "Accordingly, in mice with hindlimb ischemia, VEGF-mediated neovascularization may partially depend on the activation of SDF-1α-CXCR4 pathways." (PMID 26305217, 2015). "For instance, intravenous injection of EVs from cardiac progenitor stem cells overexpressing the C-X-C chemokine receptor type 4 (CXCR4) improved cardiac function in a rat model of ischemia/reperfusion injury when compared with control EVs without CXCR4 overexpression." (PMID 33105857, 2020). "Non-conditioned AMI induces MMP-2 release, hampering the ischemia-induced increase in SDF-1α and CXCR4 by cleaving the SDF-1α/CXCR4 axis, with diminished mobilization of the angiogenic CD34+ cells." (PMID 28299177, 2016).
Sepsis (41 papers, 2011 to 2025). Sepsis is defined as life-threatening organ dysfunction caused by a dysregulated host response to infection. "When we blocked the IFN-gamma signaling pathway using IFN-gamma deficient mice, we observed reduced susceptibility to CLP-sepsis and less CXCR4+ PD-L1+ neutrophils frequency." (PMID 40241761, 2025). "By integrating these components, we aim to provide a coherent framework for understanding the therapeutic potential and limitations of targeting CXCL12/CXCR4 in sepsis-associated ALI." (PMID 41614816, 2025). "In summary, although the CXCL12/CXCR4 axis is implicated in endothelial dysfunction in sepsis-induced ALI, its mechanistic contributions are less well characterized compared with its roles in immune and epithelial cell regulation." (PMID 41614816, 2025). "ADORA2B signaling is essential for mediating the anti-inflammatory effects of CXCR4/CXCR7 inhibition in peritonitis-associated sepsis." (PMID 41154678, 2025). "Several upregulated genes may contribute to T cell exhaustion, including PRDM1 and CXCR4 (1.32 and 0.52log2FC, respectively), which have been implicated in a murine model of sepsis." (PMID 41208955, 2025). "This study provides insights into the immune cell activation profiles associated with the worsening of the CLP-sepsis, and the CXCR4+ PD-L1+ neutrophils population highlighted here represents a promising target for therapeutic modulation in clinical sepsis hyperinflammatory phenotype." (PMID 40241761, 2025). "Notably, abrogating the IFN-gamma reduced susceptibility to CLP-sepsis and diminished CXCR4+ PD-L1+ neutrophils frequency." (PMID 40241761, 2025). "Another study showed that pharmacologic antagonism of CXCR4 with plerixafor improved the survival of mouse with polymicrobial sepsis and reduced sepsis-induced peripheral T cell loss, highlighting the crucial role of CXCR4 in controlling sepsis-induced immune dysfunction and mortality." (PMID 35048778, 2022). "Consequently, the administration of a Cxcr4 agonist prevented sepsis-associated microthrombosis and resulting tissue damage, thereby exposing a potential therapeutic strategy to foster tissue damage control in severe sepsis." (PMID 36178806, 2022). "These pathways collectively promote chemotaxis and the production of inflammatory mediators, thereby facilitating the recruitment of CXCR4-expressing neutrophils, macrophages, and lymphocytes into the inflamed pulmonary parenchyma during sepsis-induced ALI." (PMID 41614816, 2025). "Consistent with our findings, CXCR4+ immature neutrophils, also described as low-density neutrophils, which have an immunosuppressive profile, are increased in patients with sepsis." (PMID 40241761, 2025). "CXCR4 plays a pivotal role in sepsis-induced acute lung injury (SALI) through multiple intracellular signaling pathways, including NF-κB, MAPK, and PI3K/Akt." (PMID 41614816, 2025). "Despite these insights, the specific regulatory roles of CXCL12/CXCR4 signaling in pulmonary vascular endothelial cells during sepsis-induced ALI remain incompletely defined." (PMID 41614816, 2025). "The CXCL12/CXCR4 axis functions as a central regulatory hub in sepsis-induced acute lung injury (ALI), orchestrating the balance between inflammatory injury and tissue repair." (PMID 41614816, 2025). "In summary, CXCL12/CXCR4 signaling regulates AT II cell migration, proliferation, and survival, thereby playing a pivotal role in alveolar epithelial repair during sepsis-induced ALI." (PMID 41614816, 2025). "The present review examines the molecular and cellular mechanisms through which the CXCL12/CXCR4 axis shapes the course of sepsis-induced ALI." (PMID 41614816, 2025). "Through these integrative mechanisms across immune and structural compartments, the CXCL12/CXCR4 axis orchestrates both injury and repair processes in sepsis-induced ALI, underscoring its potential as a compelling therapeutic target." (PMID 41614816, 2025).
Sepsis (continued). "Together, these findings demonstrate an activation profile of CXCR4+ PD-L1+ neutrophils, exhibiting a phenotype associated with inflammation and organ damage, potentially impacting survival outcomes in the CLP-sepsis model." (PMID 40241761, 2025). "This pathway promotes CXCR4-dependent chemotaxis and facilitates the recruitment of inflammatory cells into injured lung tissue in sepsis-induced ALI." (PMID 41614816, 2025). "In experimental sepsis models, neutrophils in the pulmonary tissue show increased CXCR4 expression, which promotes their retention in the lungs." (PMID 40241761, 2025). "Further studies using AMD3100 (a CXCR4 antagonist) showed that post-sepsis and uninfected mice survived longer than control group mice." (PMID 37497001, 2023). "Comparisons involving the therapeutic effect of wild-type ASCs and ASCs transiently expressing CXCR4 and IL-10 were carried out with the aim of generating an improved anti-inflammatory response for sepsis in addition to standard antibiotic treatment." (PMID 38203690, 2023). "Administration of AMD3100, a CXCR4 antagonist, largely induces ILC2 egress, which is blocked in IL-33 deficient mice during sepsis." (PMID 35272622, 2022). "Our findings highlight the importance of a critical B-cell/neutrophil interaction during sepsis and establish neutrophil Cxcr4 activation as a potential means to promote disease tolerance during sepsis." (PMID 36178806, 2022). "In line with this idea, we found that administration of a Cxcr4 agonist improved tissue damage control during severe sepsis, indicating that Cxcr4 signaling restrains the tissue damaging properties of neutrophils during infection." (PMID 36178806, 2022). "SDF-1 and CXCR4 have also been the subject of studies showing their potential as early markers of sepsis." (PMID 36012544, 2022). "Strikingly, administration of the Cxcr4 agonist ATI2341 prevented sepsis-induced tissue damage in a dose dependent manner, whereas blocking Cxcr4 had no impact." (PMID 36178806, 2022). "Taken together, by studying a model of disease tolerance during sepsis, we here revealed a crosstalk between neutrophils and B cells in the bone marrow, in which B cells influence neutrophils likely by modulating Cxcr4 related pathways." (PMID 36178806, 2022). "At the same time, none of these treatments altered the bacterial load, suggesting that activation of Cxcr4 during sepsis induced disease tolerance." (PMID 36178806, 2022). "To determine the role of CXCR4 signaling in ILC2p egress from the BM following sepsis, we first measured cell surface expression of CXCR4 on ILC2p in BM from WT and Il33−/− mice." (PMID 35272622, 2022). "In summary, sepsis induces ILC2p egress from BM and this egress requires downregulation of CXCR4 expression by IL-33 during sepsis." (PMID 35272622, 2022). "We previously found that IL-1β-activated MSCs upregulated CXCR4 expression, promoted their migration to inflammatory sites, and improved the symptoms of sepsis in mice." (PMID 34627385, 2021). "The purpose of this study was to investigate the role of the SDF-1/CXCR4 pathway in the therapeutic effects of ERCs in a mouse sepsis model." (PMID 32256608, 2020). "In septic patients, EPC expression of CXCR-4 and high serum concentrations of VEGF, SDF-1α, and Ang-2 were associated with probability of survival, showing that the SDF-1/CXCR4 axis plays a crucial role in homing EPCs in the course of sepsis." (PMID 32599834, 2020). "Overall therefore our data warrant further studies into the role of TLR4BB and CXCR4 in LPS-induced sepsis in zebrafish as well as into the effects of early life glucocorticoid stimulation hereon." (PMID 32411141, 2020). "The expression of CXCR-4 was already shown to be increased on lymphocytes in sepsis resulting in improved migration and activation." (PMID 29796010, 2018).
Sepsis (continued). "In conclusion, we have demonstrated here for the first time that EPC in the clinical setting of sepsis exhibit a high expression of CXCR-4, RAGE and c-Kit as potential promoters of EPC homing." (PMID 29796010, 2018). "Here, we investigated the expression and function of CXCR4 in a murine model of polymicrobial sepsis." (PMID 29232699, 2017). "Results indicate that CXCR4 is selectively upregulated on naïve CD4+ and CD8+ T cells and CD4+ central memory T cells following the induction of sepsis, and that CXCR4 antagonism resulted in a significant decrease in sepsis-induced mortality." (PMID 29232699, 2017). "The data from our CLP model together with these clinical findings therefore lead us to conclude that engagement of the CXCR4/CXCL12 pathway is deleterious during sepsis." (PMID 29232699, 2017). "Because the retention and mobilization of HSPCs can contribute to changes in their BM quantity, we also attempted to evaluate the impact of sepsis on the expression of CXCR4, the key receptor involved in the maintenance of HSCs in the BM." (PMID 26272069, 2015). "In contrast, activation of the CXCR4 seemed to have positive effects on such systemic and acute diseases as sepsis or polytrauma and, there is evidence that in vivo treatment with CXCL12 analogs results in improved survival." (PMID 26375818, 2015). "In summary, the CXCL12/CXCR4 signaling axis orchestrates the recruitment, retention, activation, and reverse migration of neutrophils, thereby shaping both the onset and progression of sepsis-induced ALI." (PMID 41614816, 2025). "Having said that, a comparison of the safety and therapeutic effect of wild-type hASCs and human mesenchymal stem cells (hMSCs) transiently expressing CXCR4 and IL-10 was made, aiming to generate an improved anti-inflammatory response for sepsis, in addition to standard antibiotic treatment." (PMID 38203690, 2023). "In addition, targeting junctional adhesion molecule-C has been reported to improve sepsis-induced acute lung injury by decreasing CXCR4+ aged neutrophils." (PMID 35637483, 2022). "Previous studies have reported that the serum level of CXCR4 was much higher in neonates with sepsis than that in neonates without sepsis, indicating the diagnostic value of CXCR4 in sepsis." (PMID 35048778, 2022). "We therefore tested whether targeting Cxcr4 would be sufficient to induce disease tolerance during sepsis and treated mice with increasing doses of the Cxcr4 pepducin agonist ATI2341, or a well-established dose of the Cxcr4 antagonist AMD3100." (PMID 36178806, 2022). "We found that the expression of CXCR4 in LDN was significantly higher than HDN during sepsis, suggesting that LDNs may be in different life stages." (PMID 35027618, 2022). "We therefore investigated whether GRKs play a role in regulating CXCR4 cell surface expression on BM ILC2p in sepsis." (PMID 35272622, 2022). "More recently, Cxcr4 signaling was described to delay neutrophil aging and to protect from vascular damage in an ischemia reperfusion model, supporting our data showing the tissue protective effects of upregulated Cxcr4 on neutrophils in sepsis." (PMID 36178806, 2022). "Finally, therapeutic administration of a Cxcr4 agonist successfully promoted tissue damage control and prevented liver damage during sepsis." (PMID 36178806, 2022). "G protein-coupled protein receptor CXC chemokine receptor 4 (CXCR4) has been shown to be involved in the development of sepsis; however, it remains unclear whether CXCR4 participates in the septic myocardial injury." (PMID 35048778, 2022). "Future studies of the expression of CXCR4 on B-1a cells following eCIRP stimulation may provide deep insight into the mechanism of B-1a cell depletion from the peritoneal cavity during sepsis." (PMID 34058975, 2021). "The up-regulated expression of G-CSF in sepsis will reduce the concentration of BM CXCL12, which may cause the unstable of CXCL12/CXCR4 axis." (PMID 35006437, 2020).